CD4 (CD4 molecule)
Diseases named in the same sentence as CD4 in open-access papers (continued):
Sharing a sentence is not in itself a finding about the gene and the disease.
infection (continued). "Nevertheless, we recently demonstrated that the clonal expansion of HTLV-1 positive CD8+ and CD4+ lymphocytes relies on two distinct mechanisms: infection prevents cell death in the former whereas it recruits the latter into the cell cycle." (PMID 20222966, 2010). "Plasma viraemia increases to reach a peak after 21-28 days of infection together with depressed peripheral CD4+ T cell numbers." (PMID 20569472, 2010). "The decline of CD4+ T cells generally slowed following initiation of tenofovir therapy; CD4+ T-cell counts reached pre-infection levels in some macaques." (PMID 20824092, 2010). "SIV CP-MAC is of interest because its Env has been reported to exhibit CD4-independent utilization of rhesus CCR5 on Env-pseudotyped reporter particles, in contrast to viruses such as SIVmac239 where infection is CD4-dependent." (PMID 21203482, 2010). "The GALT is one of the largest reservoirs for SIV/HIV replication, and CD4+ T cells are massively depleted there during early infection." (PMID 20158906, 2010). "In contrast, a recent study of HIV controllers placed on ART showed that these individuals reconstituted CD4+ T cells slower than average, possibly due the their longer time of infection prior to ART initiation." (PMID 20625393, 2010). "All 36 gp120 sequences investigated conferred efficient infection of HeLa TZM-bl cells that express high levels of CD4." (PMID 20507591, 2010). "When PD-L expression on CD11c+ cells was blocked ex vivo, their ability to restimulate allogenic CD4+ T cells to produce IFNγ was restored to the level observed during acute infection." (PMID 20625513, 2010). "It was previously shown that Schistosoma mansoni co-opts CD4+ T cell-dependent mechanisms to facilitate both parasite development during pre-patent infection and the excretion of parasite eggs after the onset of oviposition." (PMID 20442785, 2010). "During re-infections, CD4+ T cell proliferation originates largely from antigen-specific memory CD4+ T cells that persist from the previous infection(s) and are re-activated by antigen-presenting DC." (PMID 21124776, 2010). "To further understand the interaction between significant variables, we next performed multivariate analyses of V1V2 length vs. time since infection, clinical stage, CD4 level, and HIV viral load after adjusting for calendar year and type of sample." (PMID 21187897, 2010). "We suggest that HIV-1 can exploit an exosome antigen-dissemination pathway intrinsic to mDCs, allowing viral internalization and final trans-infection of CD4+ T cells." (PMID 20360840, 2010). "We establish that a heterogeneous memory CD4+ T cell population develops after a primary infection, and is composed predominantly of early effector memory T cells (TemE)." (PMID 21124875, 2010). "These include TLR-induced pro-inflammatory cytokine expression, DC migration in response to the chemokine, CCL21, and, importantly, DC-mediated capture of infectious virus particles and trans-infection of CD4+ T cells." (PMID 20617179, 2010). "Monoclonal antibodies to CD4 can potently inhibit infection of T cells by primary HIV-1 isolates in vitro, including strains that are resistant to other types of HIV inhibitors." (PMID 20805996, 2010). "Second, the lack of disease progression is not due to a lack of pathogenicity of SIVs in their natural host, as there is a significant depletion of peripheral and mucosal CD4+ T cells during the acute phase of infection." (PMID 20459829, 2010). "We then examined individual subregion lengths as a function of time since infection, clinical stage, CD4 counts, and HIV plasma viral load." (PMID 21187897, 2010). "The initiation of antiviral therapy 4 hours after infection prevented CD4+ T cell depletion in rectal mucosae." (PMID 20485497, 2010). "The basal absolute amount, prior to infection, of the CD4+ T cells was found to be >100-fold higher than that of γδ T cells." (PMID 20585449, 2010).
infection (continued). "The frequency of naturally arising CD4+CD25high+ Tregs in the periphery of HCV-infected patients was reported to be higher than that in patients who resolved the infection or uninfected controls." (PMID 21047421, 2010). "This replication-independent transfer, referred to as trans-infection, requires gp120/CD4 mediated fusion into target cells, indicating that the virus must remain fully intact within the DCs." (PMID 21994702, 2010). "This notion is consistent with observations that removal of cell surface HSPG dramatically reduces the level of binding of the SU or virions to CD4+ T cells, the titer of pseudotyped virus, and the infection of CD4+ T cells and DC." (PMID 21114861, 2010). "Upon infection of mice with E. coli or treatment with LPS, the number of CD4+ and CD8α+ DCs was markedly reduced 48 hours later, a result of TLR4-TRIF signaling induced apoptosis." (PMID 21124820, 2010). "Despite the relationship between oral manifestations and CD4 count, other aspects such as the stage of the disease, the way of the transmission of infection, and the success rate of the prescribed medications are different in various societies." (PMID 23346337, 2010). "Infections in Jurkat-Raji/CD4 cocultures were carried out as before, where infection is normalized to the amount of Gag in the supernatant 48 h after mixing." (PMID 20195464, 2010). "In the airways, there was an increase in the number of all leukocytepopulations evaluated at day 5 after infection –CD4+ T cells, CD8+ T cells, NKT cells,NK cells, macrophages and neutrophils." (PMID 21079759, 2010). "Human immunodeficiency virus type-1 (HIV) envelope protein binds to the CD4 receptor and to chemokine coreceptors CCR5 or CXCR4, leading to infection and destruction of the CD4-bearing immune cells: T lymphocytes and macrophages." (PMID 21179547, 2010). "Treatment 4 hr after infection appeared to be effective against early CD4+ T cells depletion in the rectum; this efficiency was lost when treatment was started later (D7-D21, and particularly D14-D28)." (PMID 20485497, 2010). "C57Bl/6 mice maintained or slightly increased splenic CD4 numbers at d15 pi, whereas Balb/c mice had decreased CD4 numbers post-infection." (PMID 20625554, 2010). "Our initial studies indicated a detrimental role for Treg cells because depletion of CD25hi cells prior to infection, the majority of which were Treg cells, protected mice from ECM and was associated with increased antigen-specific CD4+ T cell responses." (PMID 21170302, 2010). "Increased susceptibility to C. parvum infection of mice lacking specific αβ+ T-cell subsets or MHC-II molecules or immunocompetent mice treated with anti-CD4 antibodies suggested that CD4+ T cells were more essential for the control of infection." (PMID 19247447, 2009). "Our observation of highly efficient transfer of virus from CD(-) sites for trans infection of permissive CD4(+) cells, is in keeping with other types of assay systems that have suggested that efficient trans infection can be experimentally achieved in vitro." (PMID 20011536, 2009). "This event is followed by a second phase (i.e. late transfer or cis infection) that is dependent on productive virus infection of immature DCs and on the eventual transfer of progeny viruses to CD4+ T cells." (PMID 19468304, 2009). "We were unable to confirm more of our novel epitopes in more HIV-infected subjects due to the fragile nature of CD4+ T cells at this early time point of infection and difficulty of obtaining enough CD4+ T cells from acute HIV-infected subjects." (PMID 19165342, 2009). "At day 42 post infection, the numbers of B cells and CD4+ T cells were still higher in Ceacam1−/− mice than in WT mice, while the number of CD8+ T cells was nearly identical in both mouse strains." (PMID 19621080, 2009).
infection (continued). "Infection by the H1N1 virus was accompanied by significant decrease of CD4-lymphocyte counts (p: 0.003 compared with healthy volunteers) and of B-lymphocyte counts (p<0.0001 compared with healthy volunteers)." (PMID 20037642, 2009). "Specifically, autocrine production of the chemokines MIP-1α and MIP-1β appears to be the predominant mechanism involved in protection against in vivo infection of CMV-specific CD4+ T cells." (PMID 19876388, 2009). "The percent infection defines the infection at each surface CCR5/CD4 level relative to a 100% infection at the highest CD4 and CCR5 surface density." (PMID 19360131, 2009). "Instead of requiring cytotoxic T cells, it seems that the dissemination of infection is controlled primarily with IFN-γ-producing CD4+ T cells that activate macrophages." (PMID 19436730, 2009). "In one study using P. chabaudi parasites, differences in the cytokine responses of CD4+ T cells were noted after the infection of naive mice with pRBCs versus mosquito bite." (PMID 19154991, 2009). "Because of the importance of DC-mediated trans infection of CD4+ T cells, a number of recent studies have identified factors that block this process, such as the C-type lectin, Mermaid, and natural anti-DC-SIGN antibodies in breast milk." (PMID 19486514, 2009). "In particular, we were interested in analyzing the induction of polyfunctional CD4 T cells as these have been shown to correlate with protective immunity against infections such as Leishmania major and to form the basis for a long lived memory response." (PMID 19529771, 2009). "The frequency and number of FoxP3+CD4+ Tregs was determined in each species as a function of time post-infection." (PMID 19214220, 2009). "In contrast, mice with continuous depletion of CD4+ lymphocytes showed an increasing burden of infection that remained elevated at 4 weeks after inoculation." (PMID 19558669, 2009). "In the AGM, the frequency and absolute number of circulating CD4+ T cells was lower than that of the PT prior to infection, but unchanged after infection." (PMID 19214220, 2009). "Because of the persistent active viral replication in GALT, CD4 positive cells are constantly lost from the GI tract throughout infection." (PMID 19799780, 2009). "Postintegration latency is established within days following acute infection when productively-infected CD4+ T cells revert to the resting state, becoming memory T cells." (PMID 19961595, 2009). "The date of confirmed infection ranged between 1996–2006; the median number of RNA measurements used for the calculation of the setpoint was 7, the median baseline CD4 count was 560 cells/μL, and the median age at entry was 34.1 years." (PMID 19478880, 2009). "Defining the parameters, λ is the rate of thymus production of CD4+ T cells and has units cells/(μl•day), k4 and k5 are the respective infection rate coefficients for X4 and R5 infection of CD4+ T cells and have the units μl/(virions•day)." (PMID 19680436, 2009). "DC-mediated HIV-1trans infection of CD4+ T cells is functionally distinct from cis infection and involves the trafficking of whole virus particles from the DCs to the T cells via a 'virological synapse'." (PMID 19486514, 2009). "While HIV-1 induction of CD4+ T cell death in early infection is well documented, the effects of HIV-1 on blood and mucosal B cells and their inductive microenvironments in the earliest stages of infection have not been determined." (PMID 19582166, 2009). "Previous studies in clade B infection as well as limited studies in clade C infection have shown the HIV-1 Gag protein to be the dominant target of virus-specific CD4+ T cell responses." (PMID 19352428, 2009). "The 8 most commonly targeted CD4+ T cell epitopes in B clade infection were tested for cross recognition in twenty eight randomly selected patients." (PMID 19352428, 2009).
infection (continued). "Although memory CD4+ T cells are the most frequent targets for HIV replication, they do not necessarily suffer the biggest loss during the chronic phase of infection." (PMID 19943952, 2009). "Increased numbers of CD4+ T-cells were detected in the KO mice compared to the WT mice, and antibody mediated CD4+ T-cells depletion resulted in higher levels of infection in the KO mice." (PMID 19228388, 2009). "Since CD4 T cells were preferentially recruited to the infection site, we next evaluated if these infiltrating CD4 T cells were the result of an increased turn-over rate of CD4 versus CD8 T cells." (PMID 19357780, 2009). "Memory CD4+ T cells are generated following the response of naïve CD4+ T cells to infection or immunization in the periphery and mediate immunity to re-infection." (PMID 19943952, 2009). "In the acute phase of the infection, the host usually mounts strong CD4+ and CD8+ T cell responses, but this wanes in the next few months during the transition to persistence." (PMID 20041222, 2009). "The cells display an effector phenotype and mature into multi-functional CVB3-specific memory CD4+ T cells that expand dramatically following challenge infection and rapidly differentiate into secondary effector cells capable of secreting multiple cytokines." (PMID 19834548, 2009). "Anti-TB10.4 3–11 CD8 T cells and anti-TB10.4 74–88 CD4 T cells (hereafter called CD8/10.4 and CD4/10.4 cells) represent a significant proportion of the T cells induced by infection with M.tb." (PMID 19529765, 2009). "Immunocompetent and CD4+ T-cell depleted KO mice also display delayed clearance following infection by intratracheal inoculation compared to WT mice." (PMID 19228388, 2009). "For the basic model, reinfection at later times from initial infection appears to produce higher levels of CD4+ cells." (PMID 19727394, 2009). "We evaluated Th1 cell immunity in immunized mice after vaginal challenge by quantitating the number of CD3+CD4+ cells that secrete IFNγ or IL-4 in iliac lymph nodes (ILNs) during peak infection (day 7) and during resolution of infection (day 15)." (PMID 19404403, 2009). "To facilitate enumeration of L. monocytogenes-specific CD8 and CD4 T cell responses following infection, we used strains expressing chicken ovalbumin (OVA) fused to a non-lytic fragment of LLO." (PMID 19730694, 2009). "R5 virus' level of infection is thus highest among CD62L− effector memory CD4+ T cells, where CCR5's cell surface density is highest." (PMID 19680436, 2009). "Infection with L. monocytogenes leads to a robust innate and adaptive response, characterized by the generation of long-lived antigen-specific CD4 and CD8 T cells, the latter of which are predominantly responsible for protective immunity." (PMID 19730694, 2009). "To verify, that R-848 treatment also affected lymphocyte numbers at the site of infection, we analyzed lung tissue for the content of CD4+, CD8+ and CD19+ cells." (PMID 19290047, 2009). "CD4+ T cells in the gut are rapidly infected and depleted soon after infection and CD4+ T cell repopulation of the gut is prevented throughout infection." (PMID 19799780, 2009). "The function of IL12 in peripheral infection is thought to include stimulation of CD4+ help in the CTL process." (PMID 20019816, 2009). "Although the infection process progressed at an equal rate in MDDCs infected with either R5 or X4 virus, R5 virus predominantly replicated in CD4+ T cells which are activated by antigen-presenting HIV-infected MDDCs." (PMID 19180188, 2009). "CD4 T cells are induced early during the acute phase whereas CD8 T cells have been reported to expand in the later stages of the infection." (PMID 19529765, 2009). "R5 strains, which use CCR5 for entry, are responsible for the primary infection while X4 strains, which use CXCR4, emerge later in the course of infection and are associated with a severe depletion of CD4 T cells." (PMID 19492063, 2009).
infection (continued). "The highest infection rate was at CD4 counts of less than 200 cells/μL and it was about six-fold higher compared with individuals having counts greater than 500 cells/μL (OR = 6.3; 95% CI 2.6 to 15.1)." (PMID 19765310, 2009). "This enhancing effect of sCD4 is more prominent in some strains of the related primate immunodeficiency viruses, HIV-2 and simian immunodeficiency virus (SIV), where sCD4 can efficiently replace cell-surface CD4 to drive infection of CD4−CCR5+ cells." (PMID 19343205, 2009). "Our results show that Ag85B-TB10.4/IC31® can induce high numbers of polyfunctional CD4 T cells and induce efficient protection against infection with M.tb." (PMID 19529771, 2009). "Analysis of the microarray data revealed that HIV-1 significantly influenced the transcriptomic profile of the cell population enriched in CD4+ T cells in spite of the weak infection rate." (PMID 19146679, 2009). "Although immune activation, as indicated by increased levels of Ki-67+ CD4+ T cells, was observed early in infection in all of the animals, the number of proliferating CD4+ T cells, were higher in ND than MD macaques during the chronic phase of infection." (PMID 19360097, 2009). "Although we only showed a decreased rate of infection of CMV-specific CD4+ T cells with respect to MIP-1β, this finding almost certainly extends to MIP-1α also." (PMID 19876388, 2009). "For this sample, the ratio of SIV gag copies per cell number was 29% of memory CD4+ T cells versus 5% of naïve CD4+ T cells, consistent with preferential infection of memory CD4+ T cells." (PMID 19360097, 2009). "Binding of MIP-1β or the related chemokines MIP-1α and RANTES can protect CD4+ T cells from infection by CCR5-tropic (R5) HIV." (PMID 19876388, 2009). "The marked superiority of CD4 as prognostic marker during untreated infection is furthermore supported by its estimated near 2-fold smaller proportional laboratory measurement error and physiological fluctuation within patients, compared to RNA." (PMID 19536329, 2009). "Infection of a CD4(+) target cell is the goal to which the other two options are directed, but it is also the most difficult to achieve because CD4(+) cells are relatively rare when compared to other circulating cells in the blood." (PMID 20011536, 2009). "The pDC levels were directly correlated with the degree of CD4 T cell depletion and T cell activation in both infections." (PMID 19936055, 2009). "The neutralizing activity of these antibodies has been evaluated in vitro during the infection of primary blood CD4 T lymphocytes (the principal target cells of HIV) and, more recently, with human cell lines expressing receptor and co-receptor of HIV." (PMID 21994593, 2009). "There is a paucity of data on clade C HIV-1-specific CD4+ T cell responses, despite the fact that clade C infection accounts for the majority of infections globally." (PMID 19352428, 2009). "In some series, HIV is diagnosed in immigrants and refugees at a later stage of infection, with lower CD4 cell counts, a larger proportion of females, and with different HIV subtypes." (PMID 19891861, 2009). "Infection data of cells expressing sub-maximal concentrations of CD4 and CCR5 indicates that ES-derived env clones require higher levels of receptor and co-receptor for efficient entry." (PMID 19360131, 2009). "Pre-infection (two weeks pre-infection) we observed equal amounts of Ag85B specific CD4 and CD8 T cells in the vaccinated group in the spleen." (PMID 19357780, 2009). "Within each infection group, CD4+ T cells predominantly expressed cytokines, while the CD8+ T cell response was lower than 0.05% (at this time point)." (PMID 20011586, 2009). "The non structural proteins have been described to be preferentially targeted by the CD4 +T cell responses in those who clear infection." (PMID 21994550, 2009).